CX3CL1 (C-X3-C motif chemokine ligand 1)
Diseases named in the same sentence as CX3CL1 in open-access papers (continued):
Sharing a sentence is not in itself a finding about the gene and the disease.
lung carcinoma (continued). "In summary, our results indicated that CX3CL1 furthered invasion and migration in lung cancer cells partly via activating cortactin, and CX3CL1 may be a potential molecule in regulating the migration and invasion of lung cancer." (PMID 33191645, 2021). "We observed in the experiment that the increased expression of p‐cortactin in lung cancer tissue may be due to the increased expression of cortactin, so we need more research to confirm the effect of CX3CL1 on the phosphorylation of cortactin in vivo." (PMID 33191645, 2021). "Additionally, I-309/CCL1, macrophage inflammatory protein 1α (MIP-1α)/CCL3 and granulocyte colony-stimulating factor (G-CSF) from TAM increase CX3CL1 expression on lung cancer cells." (PMID 32466280, 2020). "To determine the role of VMEC monolayers on tumor cell TEM in spines loaded with CX3CL1, we used fluorescently labeled lung cancer cells (A-549) and renal cancer cells (786-O) to assess changes in the TEM rate of cancer cells after regulating the activity of Src/P115-RhoGEF/ROCK signaling in VMECs." (PMID 32390803, 2020). "Therefore, CX3CL1 may have different functions in patients in specific contexts and among different subtypes of lung cancer." (PMID 41210693, 2025). "CX3CL1 was verified to have the potential function for predicting the prognosis of lung cancer, and this function may be attributed to its regulation of ‘positive regulation of cell adhesion’, ‘leukocyte cell–cell adhesion’, ‘leukocyte migration’ and ‘T cell activation’." (PMID 34177903, 2021). "Therefore, in the next experiment, we will further investigate the regulation mechanism of the metastasis of lung cancer by verifying whether CX3CL1 regulates the phosphorylation of cortactin through MAPK/ERK and PI3K/AKT signalling pathways." (PMID 33191645, 2021). "Similarly, in lung cancer, the CX3CL-1 expression was heightened." (PMID 34336101, 2021). "Serum CX3CL1 and CX3CR1 levels in the bone metastasis group of primary lung cancer were significantly higher than those in lung cancer patients without bone metastasis or healthy controls." (PMID 40508161, 2025). "Co-culturing macrophages with lung cancer cell lines can upregulate CCR2/CCL2 and CX3CR1/CX3CL1 in both cancer cells and macrophages, playing a central role in lung cancer growth and metastasis." (PMID 40264773, 2025). "High expression of CX3CL1 promoted nodal metastasis by activating JNK and MMP2/MMP9 activity in lung cancer cells." (PMID 40508161, 2025). "Lung cancer cells express specific chemokines (such as CXCL12/14/16, CCL7/22, CX3CL1, and XCL1) and their corresponding receptors." (PMID 39512767, 2024). "These included CX3CL1, which activates the Src/FAK signaling pathway, thereby fostering the migration and invasion of lung cancer." (PMID 38383412, 2024). "Results indicated a significant downregulation of CX3CL1, MS4A15, and GSTA1 in lung cancer cells, while EPS8L3, G6PD, KRT6A, and S100P were notably upregulated, in line with the bioinformatics analysis findings." (PMID 37315289, 2023). "Both cytokines (IL-6, 10, 17, 27, 35; TNF-α; IFN-γ; TGF-β) and chemokines (CCL-2, 5, 18; CCR-4; CXCR-4; CX3CL-1; CXCL-1, 5, 8, 13) are very commonly targeted for lung cancer treatment, considering their biomarker roles." (PMID 34336101, 2021). "In in vitro, in vivo, and ex vivo models of lung cancer, TAM-tumor cell crosstalk via the CX3CL1/CX3CR1 axis found to be crucial in lung tumor cell growth, and metastasis, suggesting a potential axis for therapeutic intervention in lung cancer." (PMID 32219066, 2020). "Little is known about CX3CL1 and CX3CR1 in cancer, particularly lung cancer." (PMID 41210693, 2025). "For example, exogenous CX3CL1 induces cell migration in H460, but not in H292 and A549, lung cancer cell lines with similar CX3CR1 expression levels." (PMID 33391453, 2021).
lung carcinoma (continued). "Therefore, in this review, we summarized the published literature from the year 2000 to the year 2019, specifically focusing on the role of IL6, TNFα, IL10, CCL2, CX3CL1, IL8 in the macrophages-tumor cells crosstalk; leading to lung cancer development and progression." (PMID 32219066, 2020).
Obesity (27 papers, 2014 to 2025). Accumulation of substantial excess body fat. "For example, microglial CX3CR1 (C-X3-C motif chemokine ligand 1) signalling determine obesity susceptibility in mice and its deficiency induces inflammation and insulin resistance in adipose tissue." (PMID 38483771, 2024). "Some previous evidences showed that CX3CL1 played an important role in the tumorigenesis of obesity-associated cancers." (PMID 35478937, 2022). "CX3CL1 has been implicated on the development of obesity-induced inflammation, and our results further demonstrate that bingeing or continuous access to HFD is capable of increasing neuroinflammatory signaling." (PMID 34067897, 2021). "In recent years, chemokines such as SDF-1/CXCL12 and fractalkine/CX3CL1 have been shown to be associated with obesity-induced hypothalamic inflammation." (PMID 30618568, 2018). "In contrast, maintaining CX3CL1-mediated microglial-neuronal interactions protects against diet-induced obesity, highlighting the importance of preserving the relationship between neurons and microglial cells to prevent obesity caused by dietary factors." (PMID 39295865, 2024). "The augmentation in the hippocampus BDNF by adipose CX3CL1 is actively working in young individuals, but it is reduced in aged individuals and in obesity conditions." (PMID 40724847, 2025). "For example, the stress alarmone and anorectic protein Gdf15 interact with members of two other groups, including inflammatory Cx3cl1, axon guidance-related protein (Bmp3), and the obesity-related proteins Timp1 and erythropoietin (Epo)." (PMID 39329749, 2024). "Inhibition of hypothalamic fractalkine (CX3CL1) reduces diet-induced hypothalamic inflammation and recruitment of BM monocytic cells to the hypothalamus, reduces obesity, and protects against glucose intolerance." (PMID 37569635, 2023). "Collectively, these data support a requirement for intact melanocortin signaling in the anti-obesity effect of microglial silencing via hypothalamic CX3CL1 overexpression." (PMID 35742824, 2022). "For instance, the elevated CX3CL1 level has been reported in the blood of patients with type 2 diabetes and obesity." (PMID 34948325, 2021). "CX3CL1 is an adipocyte-derived inflammatory chemokine which is also up-regulated in obesity and during inflammatory processes in the CNS." (PMID 34067897, 2021). "Available evidence supports a role of CX3CL1 during the early inflammatory processes observed in experimental obesity and metabolic disease." (PMID 34067897, 2021). "For instance, females are much more resistant to diet-induced obesity due to the higher expression levels of CX3CL1 than in males." (PMID 33374371, 2020). "In the second pharmacologic approach, we assessed the efficacy of CX3CL1 as an obesity treatment using an established DIO model of WT C57BL6 male mice fed HFD for 3 months." (PMID 28223698, 2017). "Dysregulation of adipose CX3CL1 may contribute to decreased BDNF levels in the hippocampus with obesity." (PMID 40724847, 2025). "Other studies have suggested that obesity increases adipose CX3CL1 expression; however, CX3CL1 augmented under obese condition may not contribute to the promotion of the BDNF level in the hippocampus." (PMID 40724847, 2025). "Interestingly, increasing brain CX3CL1 levels prevented diet-induced obesity in male mice, suggesting that the contact-dependent relationship established between microglia and neurons is crucial for maintaining energy homeostasis." (PMID 39295865, 2024). "Suggesting that obesity could lead to activation of microglia and an increase in neuroinflammation through reduced Cx3cl1 expression." (PMID 39456952, 2024). "This occurred despite the presence of endogenous CX3CL1 (at low levels due to HFD feeding), suggesting that CX3CL1-s overexpression could have pharmacological benefits for obesity treatment." (PMID 35742824, 2022). "Moreover, the anti-obesity effect of CX3CL1 is blocked in the presence of a melanocortin receptor 3/4 antagonist." (PMID 35742824, 2022).
Obesity (continued). "CX3CR1 is also expressed in subsets of peripheral monocytes and macrophages so it is possible that circulating myeloid cells that infiltrate the MBH in HFD-fed mice may also contribute to the anti-obesity effect of CX3CL1." (PMID 35742824, 2022). "Human and animal studies have observed increased CX3CL1 expression in obesity and in alcohol BD." (PMID 34067897, 2021). "Fractalkine (CX3CL1), which acts as a chemoattractant and adhesion factor, is released from adipocytes and plays a pivotal role in recruiting inflammatory cells and facilitating their settlement at inflammation sites, such as expanding white adipose tissue in cases of obesity and T2D." (PMID 40091956, 2025). "As obesity, at least in part, increases the circulating glucocorticoids and 11β-HSD1 expression in visceral adipose tissue, the increased expression of CX3CL1 in the tissue can be expected." (PMID 40724847, 2025). "In obesity, circulating monocytes express high levels of CX3CR1, indicating increased chemotactic potential toward CX3CL1 secreted by adipocytes, as evidenced by the high numbers of monocyte-derived macrophages in adipose tissue." (PMID 37569635, 2023). "In contrast to the adverse effects of visceral adipose tissue in aged humans and animals and those with obesity, the tissues in young and non-obese mice express CX3CL1 to signal to the hippocampus, thereby maintaining the BDNF protein level." (PMID 40724847, 2025). "Inhibition of CX3Cl1 reduced the glucose intolerance and fat content of obesity-prone mice without affecting their body weight." (PMID 36769012, 2023). "Based on the minocycline data, we hypothesized that the more specific microglial inhibitor CX3CL1 would restore POMC neuron function during HFD feeding, which might account for its anti-obesity properties." (PMID 35742824, 2022). "It suggests that CX3CL1, mediating early recruitment of microglia induced by HFD and thus participating in the induction of hypothalamic inflammatory response, participates in the pathogenesis of obesity as it impairs glucose tolerance and adiposity." (PMID 28855891, 2017). "In this study, the authors show that, early after HFD introduction to the mice (1–3 days), CX3CL1 is induced in hypothalamic neurons of obesity-prone mice, unlike what was observed in obesity-resistant mice." (PMID 28855891, 2017). "Considering that CX3CL1 in the peritoneal cavity signals to the hippocampus through the modulation of peritoneal immune cells, it could be speculated that the increased adipose CX3CL1 in obesity does not promote the hippocampus BDNF." (PMID 40724847, 2025). "Additionally, upregulation of FTO/CX3CL1 and suppressor of cytokine signaling 3 (SOCS3) in the hypothalamus impairs leptin- and signal transducer and activator of transcription 3 (STAT3) signaling, resulting in leptin resistance and obesity." (PMID 39125332, 2024). "Indeed, restoring CX3CL1 expression in the MBH protects from HFD-induced obesity (DIO), but the mechanisms linking CX3CL1 action—and more generally, microglial activation—to metabolic alterations remain unclear." (PMID 35742824, 2022). "A study has shown that CX3CL1-mediating early recruitment of microglia induced by HFD might contribute to the induction of hypothalamic inflammatory response and subsequently the impairment of glucose tolerance and adiposity in experimental obesity." (PMID 34948325, 2021). "Reduction of CX3CL1 expression in the hypothalamus of mice provide mild reduction in brain inflammation and glucose tolerance, but not adiposity measures and body mass, suggesting this chemokine has a specific role in controlling HFD-induced obesity-related glucose metabolism." (PMID 33324346, 2020).
Parkinson disease (27 papers, 2011 to 2026). A progressive degenerative disorder of the central nervous system characterized by loss of dopamine producing neurons in the substantia nigra and the presence of Lewy bodies in the substantia nigra and locus coeruleus. "This research group further confirmed the neuroprotective actions of soluble CX3CL1 using an adeno-associated, virus-mediated synuclein model of Parkinson’s disease." (PMID 39940727, 2025). "In these, it was described that the administration of exogenous CX3CL1 into the striatum reduced the microglial activation and loss of neurons in a Parkinson’s disease rat model based on intrastriatal administration of 6-hydroxydopamine." (PMID 39940727, 2025). "The results showed that the high expression of CX3CL1 was associated with the enrichment of the notch signaling pathway, while the low expression of CX3CL1 was linked to Parkinson’s disease." (PMID 37492566, 2023). "Indeed, some authors found that using different isoforms of CX3CL1 in a gene therapy was effective to reduce neuron loss in a rat Parkinson’s disease model, suggesting a positive role of soluble CX3CL1 in neuroprotection." (PMID 29898739, 2018). "Finally, a large single-bolus of CX3CL1 injected into the substantia nigra has been shown to induce a Parkinson disease like symptoms or even cause death." (PMID 21266082, 2011). "A review of the different publications focused on the role of this chemokine in Parkinson’s disease suggests that CX3CL1 actions contribute to preventing the loss of neurons and the excessive activation of microglia that may also result in additional brain damage." (PMID 39940727, 2025). "Its elevation suggests active neuron–microglia signaling in CJD, consistent with observations in Parkinson's disease and dementia with Lewy bodies, where CX3CL1 upregulation likely reflects a neuronal stress response." (PMID 41574640, 2026). "According to this, the responses mediated by CX3CL1 and CX3CR1 would prevent the progression of the damage associated with Parkinson’s disease within the central nervous system." (PMID 39940727, 2025). "CX3CL1, primarily expressed by neurons, plays a role in modulating microglial activity, mediating neuron‐microglia communication, and Parkinson's disease (PD) ‐related inflammation." (PMID 40613333, 2025). "Concurrently, exogenous CX3CL1 improved motor function in Parkinson's disease model mice with the Park7 knockout, promoting survival of tyrosine hydroxylase-positive neurons in the substantia nigra and reducing Iba-1-positive microglial activation." (PMID 40145975, 2025). "In this way, it was demonstrated that the soluble form of CX3CL1 reduces motor alterations, as well as dopaminergic neuronal loss and neuroinflammation in the 1-methyl-4-phenyl-1,2,3,6-tetrahydropyridine (MPTP) Parkinson’s disease model." (PMID 39940727, 2025). "In another rat model of Parkinson’s disease, CX3CL1 was shown to have a neuroprotective effect and prevented neuronal death in the striatum." (PMID 39062768, 2024). "This dual effect is dependent on the form of CX3CL1; the neuroprotective capacity of CX3CL1 lies in its soluble isoform in AD and Parkinson’s disease." (PMID 37175729, 2023). "In fact, an increase in CX3CL1 expression has been highlighted in the CSF and serum of patients with multiple sclerosis, Alzheimer’s, and Parkinson’s, already in the earliest stages of the disease." (PMID 37175729, 2023). "For example, in Parkinson’s pathology, the soluble form of CX3CL1 has been shown to have a neuroprotective effect against α-synuclein-mediated injury by reducing dopaminergic neuron loss by 40-50%; differently, the membrane form has not a similar effect." (PMID 37175729, 2023). "CX3CL1-KO mice showed altered microglial function and neurotoxicity following LPS injection as well as more neuronal damage in Parkinson’s disease and amyotrophic lateral sclerosis." (PMID 35625687, 2022).
Parkinson disease (continued). "While there is a consensus among studies for a neuroprotective role of CX3CL1 signaling in vitro, some in vivo studies even suggest a neurotoxic role of CX3CL1 as seen in animal models for Alzheimer’s- and Parkinson’s disease." (PMID 27639555, 2016). "Nevertheless, all of the different concentrations of CX3CL1 showed neuroprotection in this Parkinson disease relevant model." (PMID 21266082, 2011). "Indeed, CX3CL1 levels in serum samples obtained from Parkinson’s disease patients were found to be elevated during the initial stages of the disease." (PMID 39940727, 2025). "The results demonstrated that CX3CL1 plays a key role in the early course of Parkinson’s disease." (PMID 37175729, 2023). "In CX3CL1 knockout mouse models in which Parkinson’s was induced, only the soluble form of fraktaline was shown to inhibit neurotoxicity, accompanied by improved motor impairment, prevention of dopaminergic neuronal loss, and reduced microglial activation in animals." (PMID 37175729, 2023). "Indeed some authors showed that CX3CL1/CX3CR1 had a neuroprotective role in a rat Parkinson’s disease model and prevented oxidative stress in murine glial and neuronal cells in vitro." (PMID 30092003, 2018). "The intrastriatal 6-hydroxydopamine (6-OHDA) rat model of Parkinson disease, was used to test the hypothesis that exogenous CX3CL1 could be neuroprotective." (PMID 21266082, 2011). "Moreover, overexpression of the soluble form of CX3CL1 has been shown to mitigate neurodegeneration induced by overexpression of alpha-synuclein in a model of Parkinson’s disease, and has also been shown to reduce tau phosphorylation and improve cognition in a model of tauopathy." (PMID 32410624, 2020). "Some of the players in the outlined route like ADAM17, CX3CL1, DRD1, GRIA1, and LCAM1 have been claimed in animal model studies as therapeutic targets for Parkinson's disease." (PMID 24688734, 2013). "As a result, numerous studies have contributed to elucidate the involvement of CX3CL1 and its specific receptor CCX3CR1 in the progression of different neuroinflammatory and neurodegenerative processes, with Alzheimer’s and Parkinson’s diseases being the most studied ones." (PMID 39940727, 2025). "In a mouse model of Parkinson’s disease, CX3CR1−/− mice showed more pronounced cell death in the pars compacta of the substantia nigra than did CX3CR1+/+ mice, and similar results were obtained for CX3CL1−/− mice." (PMID 39062768, 2024). "Therefore, this study sought to determine if the CX3CL1 pathway could be a therapeutic target to prevent excessive microglia activation that contributes to neurodegenerative disease in the 6-OHDA, toxin induced, model of Parkinson's disease." (PMID 21266082, 2011).